LY6D (lymphocyte antigen 6 family member D)
Diseases named in the same sentence as LY6D in open-access papers (continued):
Sharing a sentence is not in itself a finding about the gene and the disease.
Hepatic steatosis (2 papers, 2015 to 2023). Steatosis is a term used to denote lipid accumulation within hepatocytes. "To investigate how Ly6d deficiency ameliorates diet-induced hepatic steatosis, we performed RNA-seq analysis of liver tissues from SCD-fed control mice, HFD-fed control mice, SCD-fed KD mice, and HFD-fed KD mice." (PMID 37394588, 2023). "Other examples involve genes involved in lymphocyte differentiation like Ly6d, which has been previously associated with the degree of hepatic steatosis in mice." (PMID 26604919, 2015). "In vitro and in vivo studies have revealed that Ly6d regulates hepatic steatosis by means of phosphorylation of ATP citrate lyase (Acly)." (PMID 37394588, 2023). "Mouse liver transcriptome analysis identified lymphocyte antigen 6 family member D (Ly6d) as a key regulator of hepatic steatosis and the inflammatory response." (PMID 37394588, 2023). "Inhibition of Ly6d ameliorated hepatic steatosis in a diet-induced NAFLD mouse model." (PMID 37394588, 2023). "In addition, suppression of Ly6d expression in the liver also prevented HSD-induced hepatic steatosis." (PMID 37394588, 2023). "We aimed to investigate the functional role of Ly6d in hepatic steatosis." (PMID 37394588, 2023). "To determine whether Ly6d inhibition could suppress hepatic steatosis in vitro, we compared lipid accumulation in AML12 cells treated with Ly6d-specific short interfering RNA (KD cells) and those treated with nontargeting short interfering RNA (control cells)." (PMID 37394588, 2023).
liver cancer (2 papers, 2014 to 2021). An epithelial or non-epithelial malignant neoplasm that arises from the liver. "Previously it was reported that treatment of mouse primary hepatocytes with peroxisomes proliferators (including Wy14643) for 24 hours led to upregulation of 11 genes related to liver cancer (i.e. Angptl4, Bnip3, Dbi, Fabp1, Fabp2, Fasn, HifIa, Lgals3, Ly6d, Mgll, SerpineI)." (PMID 25511156, 2014). "We found that 6 mRNA expressions were significantly different (P<0.05), including GBP6 (guanylate binding protein), TMEM (transmembrane protein), CTCFL (liver cancer marker gene), KRT5 (keratin 5), LY6D (lymphocyte antigen) and TMEM179 (transmembrane protein)." (PMID 34714841, 2021).
pancreatic adenocarcinoma (2 papers, 2022 to 2024). "The existence of LY6D surface expression in other epithelial cancers suggests that the work on BCCs will apply to more lethal cancers such as ASCP incidence in pancreatic adenocarcinoma." (PMID 36473848, 2022). "Surprisingly, LY6D+ basosquamous populations exist in many epithelial tumors, such as pancreatic adenocarcinomas, which have poor outcomes." (PMID 36473848, 2022).
steatosis (2 papers, 2020 to 2023). Increased lipid within the cytoplasm of cells. "To determine the role of Ly6d in hepatic steatosis and inflammation, we generated a Ly6d-overexpressing vector and transfected AML12 cells with it." (PMID 37394588, 2023). "In conclusion, Ly6d is responsible for the regulation of lipid metabolism, and inhibiting Ly6d can prevent diet-induced steatosis in the liver." (PMID 37394588, 2023).
anemia (1 paper, 2020). A reduction in the number of red blood cells, the amount of hemoglobin, and/or the volume of packed red blood cells. "In particular, Ly6D– CD44+ CD51– TNCs are erythroid-committed cells able to expand and differentiate into mature erythrocytes under hemolytic stresses such as sickle cell crisis and PHZ-induced anemia in mice." (PMID 33103089, 2020).
atherosclerosis (1 paper, 2022). A disease characterized by the build-up of fatty material and calcium deposition in the arterial wall resulting in partial or complete occlusion of the arterial lumen. "Cluster 5 showed a gene expression profile that was characterized by the expression of Btla, Ccr7, Tbc1d4, Ccl22, and Ly6d revealing a population of MoDC/DC cells present in the aortas that were independent of the atherosclerosis predisposition or the diet." (PMID 35159221, 2022).
basal cell carcinoma (1 paper, 2022). A carcinoma involving the basal cells. "Here we identify a pre-existing resistant cellular population in naive basal cell carcinoma tumors marked by the surface marker LY6D." (PMID 36473848, 2022).
bladder tumors (1 paper, 2025). "This expression pattern suggests that LY6D could serve as a potential differentiation marker, particularly useful for identifying squamous differentiation features of bladder tumors and for prognostic evaluation of low-invasiveness tumors." (PMID 40740240, 2025). "Our findings suggest that SLURP1 and LY6D together may promote bladder tumor growth and progression via mechanisms involving immune evasion, antioxidant stress responses, and anti-apoptosis." (PMID 40740240, 2025).
brain cancer (1 paper, 2016). A primary or metastatic malignant neoplasm affecting the brain. "Ly6D mRNA expression was increased significantly in brain cancer (n=131) than normal tissues (n=23) in Sun study." (PMID 26862846, 2016).
cervical cancer (1 paper, 2016). A primary or metastatic malignant neoplasm involving the cervix. "High Ly6D mRNA expression was also correlated in more aggressive subsets of cervical cancer, esophageal and kidney cancer in Bittner (unpublished, GSE2109), Pyeon, TCGA, Kimchi studies." (PMID 26862846, 2016).
endometrial cancer (1 paper, 2024). Primary or metastatic malignant neoplasm involving the endometrium (mucous membrane that lines the endometrial cavity). "Lymphocyte antigen 6D (LY6D) identified endometrial cancer with an AUC of 0.89 and was able to predict early-stage tumours with good accuracy." (PMID 38513301, 2024). "A three-marker panel of cervico-vaginal fluid derived proteins comprising HPT, LY6D, and C5 predicted stage I endometrial cancer with an AUC of 0.92 (0.87–0.97)." (PMID 38513301, 2024). "A 5-biomarker signature of cervico-vaginal fluid proteins combining HPT, LG3BP, FGA, LY6D and IGHM predicted endometrial cancer with an AUC of 0.95 (0.91–0.98), sensitivity of 91%, and specificity of 86%." (PMID 38513301, 2024). "A 5-biomarker panel of cervico-vaginal fluid proteins combining APOE, GGCT, CFAB, LY6D and CEAM5 predicted advanced stage endometrial cancer with AUC 0.96 (0.92–1.00)." (PMID 38513301, 2024). "A 5-biomarker panel of cervico-vaginal fluid derived proteins (HPT, LG3BP, FGA, LY6D and IGHM) predicted endometrial cancer with an AUC of 0.95 (0.91–0.98), sensitivity of 91% (83%–98%), and specificity of 86% (78%–95%)." (PMID 38513301, 2024).
fibrosis (1 paper, 2023). the formation of excess fibrous connective tissue in an organ or tissue in a reparative or reactive process. "Interestingly, genes related to liver fibrosis and inflammation (TnfR and Ly6D) were upregulated in N-RAS knockout mice challenged either with CCl4 or with BDL." (PMID 37563155, 2023).
Gorlin’s syndrome (1 paper, 2022). "By contrast, Gorlin’s syndrome patients have a low base level of spontaneous LY6D+ cells, respond well to SMOi, but induce residual LY6D+ persister tumors that recur upon SMOi cessation." (PMID 36473848, 2022).
hepatocellular carcinoma (1 paper, 2015). A malignant tumor that arises from hepatocytes. "In the inflammation category, Lgals1 (Galectin-1), an important immune response modulator and biomarker for hepatocellular carcinoma (HCC) was also markedly increased in SO-HFD but not HFD, as were Abcd2, Cd63, Ly6d and Ubd." (PMID 26200659, 2015).
kidney cancer (1 paper, 2016). Primary or metastatic malignant neoplasm involving the kidney. "Ly6D mRNA was increased significantly in Kidney cancer (n=53) than normal tissues (n=28) in Jones and Yusenko studies." (PMID 26862846, 2016).
laryngeal carcinoma (1 paper, 2024). Carcinoma that arises from the laryngeal epithelium. "LY6D was highly expressed in laryngeal cancer samples and was correlated with pathological T and clinical stages with cervical lymph node metastasis." (PMID 39727968, 2024).
liver disease (1 paper, 2023). "To investigate the potential associations between Ly6d and liver disease, we analyzed the associations between Ly6d expression and mouse liver phenotypes of the BXD family using GeneNetwork." (PMID 37394588, 2023).
mastitis (1 paper, 2024). Inflammation of breast tissue during lactation or postpartum due to an obstructed duct or infection. "Among them, cnvr_137 contains genes such as LY6D, LYNX1, LYPD2, SLURP1,THEM6, PSCA, TSNARE1, and ARC associated to clinical mastitis in US Holstein dairy cows." (PMID 38771855, 2024).
medulloblastoma (1 paper, 2016). A malignant, invasive embryonal neoplasm arising from the cerebellum. "Ly6D mRNA expression was significantly higher in medulloblastoma (n=60) than rhabdoid tumor (n=5) Pomeroy study." (PMID 26862846, 2016).
melanoma (1 paper, 2022). A malignant, usually aggressive tumor composed of atypical, neoplastic melanocytes. "Six targets—S100A9, FLG, SAMMSON, LY6D, CACNA2D2, and HES1—were found to have variable expression in different melanoma cell lines, so they could not be validated as GLI targets in melanoma." (PMID 36139698, 2022).
pancreatitis (1 paper, 2022). Inflammation of the pancreas. "We found no or very low levels of LY6D in the K19+ ducts of PAAD samples or the inflamed pancreatitis state." (PMID 36473848, 2022).
prostate (1 paper, 2020). "In particular, OLFM4 most frequently co-expressed with LY6D, a marker for prostate stem cells that are castration resistant and an origin for prostate cancer." (PMID 33318499, 2020).
triple-negative breast carcinoma (1 paper, 2011). An invasive breast carcinoma which is negative for expression of estrogen receptor (ER), progesterone receptor (PR), and human epidermal growth factor receptor 2 (HER2). "Additionally, a Ly6 family member, Ly-6D is upregulated in a variety of murine tumors and triple-negative breast cancers." (PMID 22140470, 2011).
urothelial bladder cancer (1 paper, 2020). "This study is, to our knowledge, the first to comprehensively describe the expression and clinicopathological correlates of LY6D in urothelial bladder cancer." (PMID 33042546, 2020). "The aim of this study was to further delineate the protein expression of LY6D in urothelial bladder cancer, with particular attention to its relationship with clinicopathological characteristics and patient outcome." (PMID 33042546, 2020).
urothelial carcinoma (1 paper, 2020). A malignant neoplasm derived from the transitional epithelium of the urinary tract (urinary bladder, ureter, urethra, or renal pelvis). "Of note, in line with previous observations, some tumours showed small foci of LY6D positive urothelial carcinoma cells within an otherwise completely negative setting." (PMID 33042546, 2020).
tumor (34 papers, 2007 to 2026). "Here the authors show that spatially organized and self-propagating TREM2+ tumor associated macrophages promote Ly6D- tumor cell proliferation via secretion of oncostatin M." (PMID 37164949, 2023). "Using BCCs as a model system, we have identified a spontaneously occurring resistant basosquamous state marked by LY6D surface expression and show that accumulation can be enhanced or reduced by tumor mutations or drug treatment strategies." (PMID 36473848, 2022). "In the present study, we provided evidence that LY6D played a causative role in the senescence-associated vacuole formation of tumor and normal cells." (PMID 33168631, 2021). "In some cases, there was a noticeable loss of LY6D expression in the more invasive parts of the tumour." (PMID 33042546, 2020). "On the other hand, in primary tumours from the cystectomy specimens, LY6D expression was inversely associated with N-stage and concomitant CIS, both being adverse prognostic factors." (PMID 33042546, 2020). "In the case of rBCCs, it has been made clear from this work that SMOi can lead to an accumulation of LY6D+ cells suggesting that drug intervention may drive LY6D+ cells into a similar state capable of giving rise to an SCC-associated tumor epithelium." (PMID 36473848, 2022). "This evidence would suggest that additional factors may drive cells from a BCC-associated LY6D+ state to an SCC-associated LY6D+ state with the potential to grow out an SCC-like tumor epithelium." (PMID 36473848, 2022). "In the population-based cohort, LY6D expression was higher in tumours with squamous differentiation and lower in other variant histologies compared to pure urothelial tumours, and the association of LY6D expression with survival was somewhat enhanced after exclusion of the former." (PMID 33042546, 2020). "This suggests that while Ly6D is predominantly associated with TNBC tumor." (PMID 26862846, 2016). "Thereafter, we detected an elevated expression of several tumor cell‐associated markers, including S100P, KRT17, KRT16, KRT7, and LY6D, as previously reported." (PMID 41164952, 2026). "Both SLURP1 and LY6D notably modulate the tumor microenvironment and immune responses, mechanisms that typically exert indirect impacts on tumor progression." (PMID 40740240, 2025). "FACS analysis confirmed the presence of tumour cells expressing both LY6D and EPCAM, thereby confirming the presence of this hybrid squamous-like state in primary human CRC samples." (PMID 40468074, 2025). "As a supplement, the same research team also demonstrated the mechanism regarding LY6D– tumor epithelial proliferation." (PMID 39558960, 2024). "The investigation of drug resistance mechanisms in BCC is a highly active area of research, with notable progress having been made in understanding the role of LY6D+/– tumor cells in BCC resistance." (PMID 39558960, 2024). "To extend our findings to human cells, we tested the levels of Ly6D and Ly6K proteins, which are upregulated in various tumor types 53, in 5 human tumor cell lines (HeLa, SiHa, CaSki, Detroit 562, and MCF-7) and showed their reduction after ASPH inhibition." (PMID 38356711, 2024). "SCAMs promote LY6D- tumor epithelial proliferation via secretion of the ligand oncostatin-M (OSM), a role independent of immunosuppression." (PMID 37164949, 2023). "As SCAMs were primarily localized mainly around the proliferative LY6D- tumor epithelium, we wanted to test tumor epithelial dependence on SCAMs through add-back experiments using our in vitro organoid assay in an LY6D-dependent manner." (PMID 37164949, 2023). "This difference is likely attributed to the spatial locations of the tumor epithelial populations, with SCAMs being closer to the Ly6d- tumor epithelium." (PMID 37164949, 2023). "Our previous work suggests that LY6D- tumor epithelial cells are more hair follicle and BCC-like, where LY6D+ tumor epithelial cells are more SCC-like, representing a more differentiated epidermal population." (PMID 37164949, 2023).
tumor (continued). "As previously shown, the LY6D+ cells are more spatially localized in central portions of tumor nodules and away from the HLA-DR+ cells within the tumor stroma." (PMID 37164949, 2023). "Overall, our analysis establishes SCAMs as a tumor-specific Trem2+ population within the Ly6d- LT proliferative neighborhood, suggesting a unique role within the TME." (PMID 37164949, 2023). "Beyond functioning in a spatial-dependent manner within the tumor, we show SCAMs act on a specific tumor epithelial population, promoting LY6D- tumor proliferation that directly contacts the tumor stroma." (PMID 37164949, 2023). "We found that at a local level, LY6D+ tumor epithelial cells were generally spatially segregated away from the tumor stroma." (PMID 37164949, 2023). "To determine how our global CODEX observations relate to our previous findings on tumor epithelial organization, we examined the relation of HLA-DR+ cells to the resistant LY6D+ tumor epithelium." (PMID 37164949, 2023). "They show that LY6D+ tumor cells lie on a differentiation spectrum between BCC and SCCs and labels the transition area of BSC." (PMID 38067165, 2023). "To understand the spatial localization of Trem2+ cells in relation to the different tumor epithelial states in mice, we co-stained Trem2 and Ly6d in mouse BCCs." (PMID 37164949, 2023). "We utilized several computational approaches to support the lineage progression from LY6D− to LY6D+ tumor states." (PMID 36473848, 2022). "The spatial localization of LY6D− and LY6D+ tumor populations were of great interest, prompting further investigation into their potential relationship." (PMID 36473848, 2022). "scRNA-Seq of the treated tumors revealed distinct clustering, with enhanced Ly6d levels in the SMOi treated tumor." (PMID 36473848, 2022). "We identify this population before SMOi but show that SMOi can further promote LY6D+ tumor accumulation." (PMID 36473848, 2022). "We show that LY6D+ tumor cells lie on a differentiation spectrum between BCC and SCCs, and resemble basosquamous cell carcinoma (BSC), highlighting pathway switching as a cellular plasticity-mediated resistance mechanism." (PMID 36473848, 2022). "Our analysis of multiple naive BCCs, BSCs, and SCCs suggests levels of LY6D can vary from tumor to tumor but dramatically increase along the BST spectrum towards SCC." (PMID 36473848, 2022). "RNAScope delineated the population, with LY6D marking the cells in the most central portions of tumor nodules." (PMID 36473848, 2022). "In tumor cell enriched regions, SHB, VRK2, KRT6A, GRHPR, CGA, SLC6A8, and LY6D were associated with the survival of NPC patients (P < 0.05)." (PMID 36618352, 2022). "Because the functional relevance of LY6D to tumorigenesis or tumor maintenance has yet to be described, our study hopefully leads to a better understanding of the molecular mechanism underlying malignant progression of cancer cells." (PMID 33168631, 2021). "Tumor cells plotted in second and third rows were gated on pDCs, SiglecH+Ly6D+, and NK cells CD11b+NK1.1+." (PMID 34608861, 2021). "The expression of the tumor markers in both models was similar, with an increase in the mRNA levels of Ly6d, Afp, Gpc3, Birc5, and Lyve1 being higher in DEN-treated WT mice compared to MUP-uPA, while that of Cd44 was comparable in both models." (PMID 34439245, 2021). "Tumors from MUP-uPA mice fed the HFHC diet exhibited an increased expression of tumor markers Ly6d, Cd44, Golm1, and Birc5, as well as higher levels of the proliferation marker Mki67." (PMID 34439245, 2021). "In some cases, LY6D expression was uniformly strong in the superficial part and more scattered in the invasive parts of the tumour." (PMID 33042546, 2020). "In the two cohorts with mixed stages, positive LY6D expression was denoted in 63 and 64% of the cases, respectively, and found to be significantly higher in low-grade and less invasive tumours." (PMID 33042546, 2020).